ALMS1 (ALMS1 centrosome and basal body associated protein)
Description:
Involved in PCM1-dependent intracellular transport. Required, directly or indirectly, for the localization of NCAPD2 to the proximal ends of centrioles. Required for proper formation and/or maintenance of primary cilia (PC), microtubule-based structures that protrude from the surface of epithelial cells.
Synonyms: KIAA0328; ALSS
Tractability: PROTAC: ubiquitination databases record sites on it; its protein half-life has been measured.
Gene: Protein-coding gene on chromosome 2 (73,385,758 to 73,625,166, forward strand). Ensembl gene ENSG00000116127.
Subcellular location: Cytoplasm; Cytoplasm, cytoskeleton, microtubule organizing center, centrosome; Cytoplasm, cytoskeleton, cilium basal body; Cytoplasm, cytoskeleton, spindle pole
Subcellular location (Human Protein Atlas): Basal body; Centrosome; Cytosol; Flagellar centriole; End piece; Microtubules; Mid piece; Nucleoplasm
Pathways (Reactome):
Cell Cycle: AURKA Activation by TPX2; Loss of Nlp from mitotic centrosomes; Loss of proteins required for interphase microtubule organization from the centrosome; Recruitment of NuMA to mitotic centrosomes; Recruitment of mitotic centrosome proteins and complexes; Regulation of PLK1 Activity at G2/M Transition
Organelle biogenesis and maintenance: Anchoring of the basal body to the plasma membrane
Gene Ontology:
Molecular function: protein binding
Biological process: endosomal transport; regulation of stress fiber assembly; positive regulation of cold-induced thermogenesis; regulation of centriole replication
Cellular component: centriole; centrosome; ciliary basal body; cytosol; microtubule cytoskeleton; cytoplasm; spindle pole
Genetic constraint (gnomAD): Loss-of-function variants: 266 observed, 356.98 expected, observed/expected ratio (o/e) 0.75, 90% interval 0.67 to 0.82. The upper end of that interval is the gene's LOEUF score, 0.82, which puts it in group 3 of 6, group 1 being the genes least tolerant of losing a copy. Missense variants: 5,388 observed, 5,058.5 expected, observed/expected ratio (o/e) 1.07, 90% interval 1.04 to 1.09. Synonymous variants: 1,839 observed, 1,836.1 expected, observed/expected ratio (o/e) 1, 90% interval 0.96 to 1.04.
Gene-disease validity (ClinGen):
ClinGen rates the evidence that ALMS1 causes each of these diseases.
Alstrom syndrome (autosomal recessive): Definitive. A multisystemic disorder characterized by cone-rod dystrophy, hearing loss, obesity, insulin resistance and hyperinsulinemia, type 2 diabetes mellitus, dilated cardiomyopathy (DCM), and progressive hepatic and renal dysfunction.
Homologues: Orthologues: chimpanzee ALMS1 (98% identical), macaque ALMS1 (91% identical), pig ALMS1 (62% identical), dog ALMS1 (59% identical), rabbit ALMS1 (58% identical), guinea pig ALMS1 (55% identical), mouse Alms1 (47% identical), rat Alms1 (46% identical), tropical clawed frog alms1 (16% identical). Paralogues in human: CEP295 (8% identical), C10orf90 (4% identical), CEP295NL (2% identical).
Diseases named in the same sentence as ALMS1 in open-access papers:
ALMS1 is named in the same sentence as 122 diseases in open-access papers, as found by Europe PMC text mining. Sharing a sentence is not in itself a finding about the gene and the disease. The quoted sentences say what the papers report.
Alström syndrome (95 papers, 2007 to 2026). "Alström syndrome 1 (ALMS1) is a protein linked to Alström syndrome, a rare genetic disorder characterized by obesity, insulin resistance, hyperinsulinemia, and hypertension." (PMID 41691606, 2026). "In Alström syndrome, a rare multisystem disorder mainly caused by nonsense mutations in the ALMS1 gene, patients often present with infantile cardiomyopathy, retinal dystrophy, type 2 diabetes, and hearing loss in addition to obesity." (PMID 41751610, 2026). "Alström syndrome (ALMS) is a rare autosomal recessive multisystem disorder caused by biallelic pathogenic variants in the ALMS1 gene, characterized by progressive cone-rod dystrophy, early-onset obesity, cardiomyopathy, and multiorgan dysfunction." (PMID 41466426, 2025). "Of particular interest is Alström syndrome, which is caused by a mutation in Alms1, a gene involved in ciliogenesis." (PMID 40676250, 2025). "ALMS1 mutations can lead to Alström syndrome in humans, in which dilated cardiomyopathy is reported in infants and restrictive cardiomyopathy is reported in adults." (PMID 40306862, 2025). "Alström syndrome (ALMS) is an ultra-rare metabolic disorder caused by biallelic loss-of-function in the Alms1 gene which encodes a ubiquitously expressed centrosomal protein of the primary cilium." (PMID 40676683, 2025). "This study provides the most comprehensive clinical and genetic characterization of Alström syndrome in a Chinese cohort to date, identifying 64 novel ALMS1 variants and expanding the known mutational spectrum of this rare disorder." (PMID 41466426, 2025). "Understanding if Alms1 function in centriole duplication is conserved in humans is a future challenge as ALMS1 is the only gene associated with the extremely rare Alström syndrome in humans." (PMID 40021845, 2025). "Alström syndrome (AS), a multisystem disorder caused by biallelic ALMS1 mutations, features major early morbidity and mortality due to cardiac complications." (PMID 38756069, 2024). "This study presents a Saudi female patient with Alström syndrome confirmed by genetic testing that verified the autosomal recessive inheritance of an extremely rare ALMS1 mutation." (PMID 38883102, 2024). "ALMS1, the protein encoded by the ALMS1 gene, causes Alström syndrome through ALMS1 gene polymorphisms." (PMID 38970022, 2024). "Alström syndrome (AS) is an autosomal recessive disorder caused by biallelic loss-of-function mutations in the ALMS1 gene." (PMID 38756069, 2024). "Mutations in the gene that codes for the ALMS1 protein have been implicated in heart failure in infants before any other signs of Alström syndrome have developed." (PMID 38756069, 2024). "Alström Syndrome (AS), caused by biallelic ALMS1 mutations, includes obesity with disproportionately severe insulin resistant diabetes, dyslipidemia, and fatty liver." (PMID 38583571, 2024). "Alström Syndrome is an autosomal-recessive monogenic disease caused by homozygous or compound heterozygous variants in the ALMS1 gene." (PMID 39060957, 2024). "Alström syndrome (AS), caused by biallelic loss-of-function ALMS1 mutations, features childhood-onset retinal degeneration, deafness, obesity, diabetes mellitus, and cardiomyopathy." (PMID 38583571, 2024). "ALMS1 has been consistently associated with chronic kidney disease in population studies and in a monogenic disorder (Alstrom syndrome, OMIM #203,800), and obesity and insulin resistance in experimental models." (PMID 37461045, 2023). "Alström syndrome (ALMS) is a rare autosomal recessive disease that is associated with mutations in ALMS1 gene." (PMID 38062477, 2023). "In conclusion, our results not only expand the spectrum of mutations in BBS and ALMS1 genes but also accentuate the importance of genetic testing for differentiating BBS from Alström syndrome." (PMID 35912300, 2022).
Alström syndrome (continued). "This study revealed four novel pathogenic variants of ALMS1 gene and analyzed the clinical phenotype of the three patients and the other members in two Chinese families with Alström Syndrome." (PMID 36162988, 2022). "Mutations in ALMS1 can cause Alström syndrome, an autosomal recessive disorder that affects multiple organs where patients typically develop type 2 diabetes in childhood or adolescence." (PMID 36344967, 2022). "One neonatal HS carried compound heterozygous ALMS1 gene mutation, which presented as Alström Syndrome." (PMID 36440223, 2022). "We found two new compound heterozygous pathogenic variants of the ALMS1 gene and determined the diagnosis as Alström Syndrome in three patients of two Chinese families." (PMID 36162988, 2022). "It is noteworthy that three probands (47, 48, and 49) were endowed with different homozygous variants, c.6299C>A p.(Ser2100*), c.7471_7472del p.(Ser2491Thrfs*5), and c.11410C>T p.(Arg3804*), respectively, in ALMS1, causing Alström syndrome (OMIM 203800)." (PMID 34148116, 2022). "The Alström Syndrome patients belonged to a Tunisian family and ALMS1: c.10388-2A>G variant was identified as the likely cause of the condition." (PMID 34609590, 2022). "Five of our probands exhibited ciliopathies due to variants in ALMS1 (Alström syndrome) and CEP78 (CRDHL1)." (PMID 34148116, 2022). "In conclusion, Alström Syndrome is a rare autosomal recessive cilia disease that causes retinal cone-roll dystrophy and systemic lesions due to the association of ALMS1 protein with cilia function." (PMID 36162988, 2022). "ALMS1 is the gene responsible for Alström Syndrome, a ciliopathy characterized by hearing and vision loss in addition to obesity and diabetes." (PMID 33793549, 2021). "Mutations in the ALMS1 gene are associated with the development of Alstrom syndrome in human beings, a multisystem familial disease that can include retinal degeneration, obesity, neurosensorial deafness, type 2 diabetes and cardiomyopathy." (PMID 33639992, 2021). "Loss of function mutations of ALMS1 have been implicated in Alstrom syndrome (AS) [OMIM 203800], a rare recessive ciliopathy that has been associated with cardiomyopathy." (PMID 34387706, 2021). "One proband harboured a homozygous rare nonsense variant in ALMS1 consistent with a diagnosis of Alstrom’s syndrome, a disorder characterised by childhood obesity, visual impairment, hearing loss, and cardiomyopathy." (PMID 34748544, 2021). "Cardiomyopathy associated with mutations in the ALMS1 gene is most often observed in conjunction with other multisystemic effects of Alstrom syndrome, however, some patients develop isolated cardiomyopathy in the absence of multisystemic disease." (PMID 33639992, 2021). "Mutations in the ALMS1 gene are associated with the development of Alstrom syndrome, a multisystem familial disease that can include cardiomyopathy (dilated, restrictive)." (PMID 33639992, 2021). "Mouse model of Alström syndrome with truncated ALMS1 protein shows cilia loss from kidney proximal tubules." (PMID 32276433, 2020). "Actually, ALMS1 is the only gene associated with the Alström syndrome and pathogenic variants are usually nonsense or frameshift mutations, resulting in a truncated protein." (PMID 32396277, 2020). "The use of WES detected a pathogenetic mutation in ALMS1, enabling the definitive diagnosis of Alström syndrome." (PMID 32396277, 2020). "Major criteria include: a pathogenic mutation in one ALMS1 allele/or family history of Alström syndrome, nystagmus, legal blindness, cone-rod dystrophy." (PMID 31810438, 2019). "Here we present clinical features in two siblings diagnosed with Alström syndrome associated with two novel changes in ALMS1." (PMID 31810438, 2019). "Three out of 4 cases with clinical suspicion of Alström syndrome carried biallelic causal ALMS1 variants (families RP-1232, RP-2177, and RP-2186)." (PMID 29588463, 2018).
Alström syndrome (continued). "RFX1 controls ALMS1 gene expression by binding to X-boxes, and mutation of ALMS1 causes Alstrom syndrome, a primary ciliopathy." (PMID 29298325, 2018). "In the two patients with a prior clinical diagnosis of Alström syndrome but only missense variants in ALMS1, ALMS1 expression in cells was normal." (PMID 28717663, 2017). "Currently, more than 20 BBS genes have been identified and ALMS1, the causative gene for Alstrom syndrome which has significant phenotypic overlap with BBS." (PMID 29479522, 2017). "It remains possible that ALMS1 plays other roles in cells unrelated to primary cilia, however, and that it is loss of such functions that relates to the tissue pathology of Alström Syndrome." (PMID 28717663, 2017). "We have now studied 23 primary dermal fibroblast lines from patients with a clinical diagnosis of Alström syndrome, all of whom had undergone mutational analysis of the ALMS1 gene." (PMID 28717663, 2017). "Over 120 mutations in ALMS1 are known to cause Alstrome syndrome (Online Mendelian Inheritance in Man accession number 203800), a rare multi-systemic disease with less than 1,000 reported cases world-wide." (PMID 28135309, 2017). "Mutations in Alms1 cause Alstrom's syndrome, which is an autosomal recessive syndromic genetic disorder with sensorineural hearing loss." (PMID 28725177, 2017). "Alström Syndrome is a rare autosomal recessive, monogenic disorder caused by mutations in the ALMS1 gene." (PMID 27142762, 2016). "Mutations in FAM161A are reported to be associated with early onset recessive retinitis pigmentosa while mutations in ALMS1 are associated with Alstrom syndrome and non-syndromic Leber’s congenital amaurosis." (PMID 26352687, 2015). "Alström Syndrome, a recessive ciliopathy, caused by mutations in ALMS1, is characterized by progressive metabolic alterations such as childhood obesity, hyperinsulinemia, and type 2 diabetes." (PMID 25299671, 2014). "The gene responsible for Alström syndrome, ALMS1, is ubiquitously expressed and has multiple splice variants." (PMID 22693585, 2012). "Alström syndrome is caused by mutations in ALMS1, a large gene comprised of 23 exons and coding for a protein of 4,169 amino acids." (PMID 22043170, 2011). "Alström Syndrome is caused by mutations in ALMS1, a large >230 kb gene located on chromosome 2p13 with ubiquitous expression in most tissues affected." (PMID 21541333, 2011). "To date, 109 different mutations in ALMS1 have been identified in individuals with Alström syndrome and the majority are nonsense and frameshift (insertions or deletions) that result in premature termination codons." (PMID 22043170, 2011). "Alström syndrome is caused by mutations in the ALMS1 gene, located on chromosome 2p13, and is inherited as an autosomal recessive disorder." (PMID 22043170, 2011). "Since Alström syndrome is caused by mutations in the ALMS1 gene, molecular genetic analysis can be used to confirm the clinical diagnosis." (PMID 22043170, 2011). "Sequencing and further characterization of fat aussie revealed a mutation in Alms1, and fat aussie is emerging as a good animal model for understanding Alström syndrome and the function of cilia-localized Alms1." (PMID 19956802, 2009). "This phenotype is similar to human Alström syndrome, which is caused by mutation in the ALMS1 gene." (PMID 19956802, 2009). "We have reported here two novel missense mutations in the ALMS1 gene causative for Alstrom syndrome in an English kindred." (PMID 18154657, 2007). "ALMS1 mutations account for the preponderance of Alström syndrome cases." (PMID 39060957, 2024). "Genetic alterations in the ALMS1 gene are the cause of Alström syndrome." (PMID 38883102, 2024). "Our study further contributes to the realm of Alström syndrome genetics in Saudi Arabia and globally by detailing two siblings harboring the homozygous pathogenic nonsense mutation, c.2729C>G, within exon 8 of the ALMS1 gene." (PMID 37937857, 2023).
Alström syndrome (continued). "ALMS1, which has been reported to cause Alström syndrome, had 12 variants in our study." (PMID 37327085, 2023). "Homozygous or compound heterozygous variant mutations in the ALMS1 gene may cause Alström syndrome (MIM#606844), characterized by a progressive loss of vision and hearing, heart disease, obesity, T2D, and short stature." (PMID 38162681, 2023). "However, we identified a novel variant in the ALMS1 gene (c.10996delC, p.Q3666fs) indicative of Alström syndrome." (PMID 35912300, 2022). "The hearing loss seen in Alström Syndrome may be due in part to hair cell defects as Alms1 mutant mice show stereocilia polarity defects and a loss of hair cells." (PMID 33793549, 2021). "Genotype–phenotype correlations for ALMS1 splice site mutations in Alström syndrome patients." (PMID 33981653, 2021). "Mutation in ALMS1 was reported to cause Alstrom syndrome and LCA." (PMID 33957996, 2021). "Alström syndrome is a rare recessively inherited disorder caused by variants in the ALMS1 gene." (PMID 32867697, 2020). "Alström syndrome (ALMS) is a very rare autosomal recessive monogenic disorder caused by a mutation in the ALMS1 gene and characterised by childhood onset obesity, dyslipidaemia, advanced non-alcoholic fatty liver disease, diabetes and extreme insulin resistance." (PMID 30477455, 2018). "Alström syndrome (AS), featuring retinal dystrophy, neuronal deafness, cardiomyopathy, metabolic syndrome, and diffuse fibrosis, is caused by biallelic mutations in the centrosomal protein ALMS1." (PMID 28717663, 2017). "ALMS1 mutations cause Alstrom syndrome, a rare genetic disorder." (PMID 28135309, 2017). "Defects in ALMS1 cause Alstrom syndrome [MIM: 203800], an autosomal recessive disorder characterized by progressive cone-rod dystrophy leading to blindness, sensorineural hearing loss, childhood obesity associated with hyperinsulinemia, developmental delay, and late onset type 2 diabetes mellitus." (PMID 27788217, 2016). "Our findings expand the spectrum of ALMS1 mutations causing Alström syndrome." (PMID 22876109, 2012). "BBS shares many similarities with Alström syndrome, caused by mutations in the gene ALMS1 and inherited in an autosomal recessive manner, but Alström syndrome (ALMS) is characterized by relative preservation of cognitive function and the absence of polydactyly." (PMID 21843323, 2011). "The loss or the dysfunction of ALMS1 might facilitate the transport of the 11-cis retinoids to the outer segment, thus enhancing cone chromophore turnover and contributing to the deterioration of cones in Alström syndrome." (PMID 37252956, 2023). "Thus far, ALMS1 (NM_015120) is the only gene associated with Alstrom syndrome (AS)." (PMID 33782391, 2021). "Alström syndrome (ALMS) is a rare autosomal recessive multi-organ syndrome considered to date as a ciliopathy and caused by variations in ALMS1." (PMID 32973878, 2020). "Alström Syndrome (ALMS) is an ultra-rare multisystem genetic disorder caused by autosomal recessive variants in the ALMS1 gene, which is located on chromosome 2p13." (PMID 32958032, 2020). "Although the ALMS1 gene is one of the largest disease-associated genes identified today in the human genome, its physiological function and pathological significance both for the etiology of Alstrom syndrome and carcinogenesis remains largely unknown." (PMID 28135309, 2017). "Mutations in ALMS1 are responsible for a rare ciliopathy, the Alström syndrome, but how ALMS1 controls ciliary functions is still enigmatic." (PMID 40021845, 2025). "In Alström syndrome, diabetes is common due to ALMS1 gene-related defects in ß-cell function and peripheral insulin signaling." (PMID 41480351, 2025). "Patient IRD-26 presented with variants in two genes, ALMS1 and MKS1, which are typically linked to syndromic ciliopathies, including Alström syndrome, Meckel syndrome, Bardet–Biedl syndrome, and Joubert syndrome." (PMID 41465088, 2025).